BCL2 (BCL2 apoptosis regulator)
Diseases named in the same sentence as BCL2 in open-access papers (continued):
Sharing a sentence is not in itself a finding about the gene and the disease.
tumor (continued). "The combination of MYC, BCL2, and P53dd led to tumor formation with a median of 111 days and the combination of MYC, BCL2, and BCL6 resulted in tumor formation with a median of 108 days." (PMID 31586074, 2019). "We found that a variety of tumor progression-related genes were involved, such as apoptosis-related genes (FAS, BCL2, and BCL2L11) and a gene associated with DNA repair (BRCA1)." (PMID 30984308, 2019). "Immunoreactivities for XIAP, Bcl2, and Bax were mainly detected in cytoplasmic compartments and was heterogeneously distributed within tumor lesions." (PMID 30943930, 2019). "These typically have focussed on the BCL-2 pro-survival proteins that are often over-expressed in tumor cells, and contribute to tumorigenesis and drug resistance." (PMID 31019203, 2019). "We found that PCNA and Bcl-2 were increased in tumor cells co-cultured with activated 3T3, while the expression of Bax was decreased." (PMID 31167491, 2019). "Maximizing the percentage ratio of Bax to Bcl-2 protein expression in tumor cells from combined treatment (Biobran + Rad) resulted in activation of caspase-3 pathway." (PMID 31504707, 2019). "There is also a very low apoptotic activity in residual tumor cells supported by very low expression of Bax and cleaved caspase 3 by residual tumor cells and high expression Bcl2 and AKT-1 by residual tumor cells." (PMID 30744593, 2019). "It is therefore required that drug-resistant mutants of BCL-2 retain the ability to bind pro-apoptotic BH3 motifs to maintain the tumour’s viability." (PMID 31160589, 2019). "We showed that these mRNA targets for lncRNAs in the ceRNA network included a variety of tumor-associated genes, such as the apoptosis-related genes FAS, BCL2, and BCL2L11 and the DNA repair gene BRCA1." (PMID 30984308, 2019). "Obatoclax mesylate (known as GX15-070) is another BCL-2 inhibitor, and the combination of obatoclax with radiation showed tumor control in nasopharyngeal carcinoma, prostate cancer, and leukemia." (PMID 31370269, 2019). "The miR-204 acts as tumor suppressor in human cancer by targeting BCL2 at an early-stage, and, thus protecting cancer cells from undergoing apoptosis as a resistance to androgen deprivation therapy." (PMID 31756185, 2019). "The level of Bcl-2 in tumor cells was influenced with the treatment of TNuF, irradiation or both to various extents." (PMID 31426614, 2019). "In the preclinical setting, venetoclax (ABT-199), a Food and Drug Administration (FDA)-approved anti-Bcl2 drug, was showed to increase anti-tumor effects of doxorubicin on subcutaneously injected MDA-MB-231 cells in xenograft models." (PMID 31652963, 2019). "The conjugate silenced PKL1 and Bcl2 genes with 85 and 90% efficiency, respectively, in the xenographic prostate LNCaP tumor-bearing mice model after 10 intratumoral injections; a decrease in tumor growth and regression were also observed." (PMID 31105570, 2019). "If specific tumours are dependent upon Bcl-2, then BH3-mimetics with a single-molecule specificity would be desirable to minimise adverse effects." (PMID 31681471, 2019). "A potential mechanism by which LBPs exert its anticancer effects is by regulating tumor apoptosis via the Bax and Bcl-2 expression and induce cell cycle arrest of a variety of cancer cells at G0/G1, S, or G2/M phase." (PMID 30891458, 2019).
tumor (continued). "Robust activation of MYC-associated apoptosis by combined BCL-2/BCL-XL inhibition and AMPK activation suppressed tumor growth, offered survival benefits, and increased the infiltration and activity of immune cells in the tumor tissue." (PMID 30728358, 2019). "Costunolide increased the expression of cleaved caspase 9, cleaved caspase 3 and Bax proteins and decreased the expression of Bcl-2 protein in xenografted tumor." (PMID 31242894, 2019). "Accordingly, the levels of PCNA and Bcl‐2 were significantly lower in xenograft tumour tissues collected from the SNHG16 knockdown than the control group (P < .05)." (PMID 31483572, 2019). "We showed that the mRNA targets for lncRNA RP11-399O19.9 included a variety of tumor-associated genes, such as the apoptosis-related genes FAS, BCL2, and BCL2L11." (PMID 30984308, 2019). "In the context of our findings, mir-148a under-expression in tumor and stroma potentially leads to increased expression of its target genes such as BCL2, GRIN2B, and SELL, which play roles including adaptive immune system regulation." (PMID 31150430, 2019). "Previous work has suggested that BCL2 overexpression is predictive of a differentiation response rather over induction of apoptosis in cultured tumor cell lines." (PMID 31234811, 2019). "In vivo, it inhibits tumor growth in a mouse xenograft model as it interacts with the 3′UTR BCL2, a well-known antiapoptotic oncoprotein." (PMID 31681586, 2019). "To investigate the underlying antitumor mechanism of TMEA against SW620 tumor xenografts in vivo, we investigated the effects of TMEA on the expression of CD31, Bcl-2, Bax, and caspase-3 and compared to that of 5-FU treatment." (PMID 32047442, 2019). "Combining BRAFi or MEKi with pan-BCL2/BCL-w/BCL-XL inhibitors causes strong synergistic cell death of CRC, NSCLC and pancreatic cells and tumour regressions." (PMID 31727888, 2019). "miR-181a functions as a tumour suppressor, with re-expression of miR-181a inhibiting proliferation, migration, and invasion and promoting apoptosis (though regulation of Bcl-2) in cancer cells." (PMID 31077182, 2019). "BCL-XL is an anti-apoptotic member of the B cell lymphoma 2 (BCL-2) protein family whose overexpression contributes to tumor progression and resistance to chemotherapeutic agents." (PMID 30770954, 2019). "The implication of altered Bcl-2 protein expression in tumours is that the sensitivity of those tumours to apoptosis in response to a variety of therapies will change." (PMID 31681471, 2019). "At the same time, some studies believed that the expression of Bcl-2 was one of the mechanisms of tumor resistance, and expression of Bcl-2 in tumor cells was detected during the treatment of triphenylamine (TAM)." (PMID 30956677, 2019). "Marsdenia tenacissima induced apoptosis in tumor cells by regulating the Caspase 3, Caspase 9, Bak, Bax, Bcl-xl, Bcl-2, Fas, and PKC genes, as well as the PI3K/AKT/mTOR and the Hippo signaling pathways." (PMID 31341493, 2019). "The expression of a proliferation indicator (PCNA) and an anti‐apoptosis protein (BCL‐2) was analysed in each group of tumour tissues." (PMID 31318114, 2019). "Unbalanced Bax/Bcl-2 ratio suggested that anti-apoptotic mechanisms are critical for tumour growth in ACC." (PMID 30736793, 2019). "Several anti-apoptosis proteins such as survivin and Bcl-2, which are known to be crucial for tumor survival, represent targets of the transcription factor STAT3 and are down-regulated as a consequence of STAT3 inhibition." (PMID 30914735, 2019). "This suggests that a high level of phosphorylated AKT is a predictive indicator of tumor cell sensitivity to the combination of maritoclax and a BCL-2/xL inhibitor." (PMID 31150457, 2019).
tumor (continued). "This is due to that fact that co-delivery of DOX and Bcl-2 siRNA produce a synergistic anti-tumor effect in which sensitivity of HepG2 cells to DOX was enhanced owing to down-regulation of BCL-2 by RNA interference." (PMID 30723405, 2019). "This understanding can be used both to test how a tumour’s Bcl-2 landscape determines how it will respond to chemotherapy and to therapeutically manipulate that landscape to sensitise or kill cancer cells." (PMID 31681471, 2019). "NF-κB was shown to improve the anti-apoptotic activity of tumor cells by regulating the transcription of Bcl-2, leading to drug resistance of tumor cells." (PMID 30849956, 2019). "The activation of BECN1 is followed by direct phosphorylation of B-cell lymphoma 2 (BCL2), which in turn disrupts the interaction between BECN1 and BCL2 and induces autophagy in tumor cells." (PMID 31861079, 2019). "Bcl-2 expression was considered as positive when at least 65% of tumor cells were immunohistochemically stained." (PMID 30630524, 2019). "The treatment resulted in the reduction of known CDK9 targets, i.e. Bcl‐2 and Mcl‐1 in tumour tissues." (PMID 31398271, 2019). "We further show that it is possible to use native siRNA (without further chemical modifications or formulation beyond PEGylation) to regulate Bcl-2 expression and reduce tumor growth in vivo." (PMID 30801019, 2019). "Preclinical studies have shown that the Bcl-2/Bcl-xl dual target inhibitor ABT-737 significantly enhances the anti-tumor effects of chemotherapy and radiotherapy and is effective in a variety of hematological and solid tumors." (PMID 31892356, 2019). "In most tumor tissues and cancer cell lines, the anti-apoptotic Bcl-2 proteins are frequently highly expressed." (PMID 31057406, 2019). "Clinical tumor-based analysis also confirmed the inverse correlation between Cx43 and Bcl-2 expression." (PMID 31766723, 2019). "More recently, the same authors involved a similar system incorporating a folic acid targeted group (MPEG-PCL-PEI-FA/α-CD) to co-deliver the chemotherapeutic paclitaxel and the antipoptotic Bcl-2 conversion gene in a tumor of mice." (PMID 30960498, 2019). "This study aimed to test the role of Cx43 protein on Bcl-2 expression, tumor progression and response to taxane-based treatment in HNSCC." (PMID 31766723, 2019). "In NB, in vitro studies have demonstrated that Bcl-2 is highly expressed, and its expression is inversely correlated to the number of apoptotic cells and the level of differentiation of the tumor." (PMID 31664947, 2019). "Previous studies have revealed critical roles of BCL-xL and MCL-1 in tumor cell response to BCL-2/BCL-xL/BCL-w inhibition." (PMID 30250075, 2018). "The results at week 3 demonstrate a significant delay in tumor progression observed when NSCs are modified to overexpress Bcl-2 using either the adenoviral or the minicircle vector." (PMID 30026762, 2018). "Systemic administration of a siRNA designed to trigger RIG-I and silence Bcl2 induced DC-dependent production of IFNs and strongly inhibited tumor growth in B16 melanoma model." (PMID 29686682, 2018). "This kind of tumor presented mostly moderate expression (score 2) for Bcl-2 protein (n = 11/55%), which was a predominantly cytoplasmic and diffuse expression among the tumor cells." (PMID 29476674, 2018). "The suppression of MYCN expression increased the levels of Bax and decreased the levels of Bcl‐2 and cyclin D1 proteins in cell‐derived tumour xenografts." (PMID 29673070, 2018). "The results of in vivo study further confirmed that Shikonin suppressed afatinib-resistant NSCLC xenograft tumor growth by decreasing p-Akt, Bcl-2 expression and increasing cleaved caspase-3, Bax expression." (PMID 30420490, 2018). "To determine if metformin potentiates the anti-tumor activity of novel targeted agents, we tested the combination of metformin with either a bcl-2 inhibitor (Venetoclax) or CDK9 inhibitor (BAY-1143572) or PI3K inhibitor (Idelalisib)." (PMID 29765528, 2018).
tumor (continued). "CEPs impact intratumoral blood flow and suppress tumor growth by downregulating Bcl-2 and upregulating expression of bax and caspase 3/7." (PMID 30305062, 2018). "BC094916 overexpression suppressed Creb1 and Bcl2 transcription to induce cell apoptosis, which suppressed SP 2/0 proliferation and xenograft tumor progression." (PMID 30220882, 2018). "The BCL2/BAX ratio in each renal biopsy analysed was higher in tumour tissue with respect to control tissue due to reduced BAX level." (PMID 29251173, 2018). "In conclusion, the data presented in this study demonstrate for the first time that the suppressive effect of gAcrp on tumor growth is mediated via destabilization of Bcl‐2 mRNA." (PMID 30524947, 2018). "An existing study shows that inhibiting the binding of CTLA-4 and its ligands also can downregulate Bcl-2 and promote the apoptosis of tumor cells." (PMID 30564277, 2018). "We used the ELISA assay to investigate the effects of TF on the levels of BAX and Bcl-2 in tumor tissues of H22 tumor-bearing mice." (PMID 29636773, 2018). "In HCC, HNF1A-AS1 functioned as an oncogene in tumor growth and apoptosis through sponging tumor-suppressive miR-30b-5p and de-repressing Bcl-2 and HNF1A-AS1-miR-30b axis significantly promoted autophagy under starvation." (PMID 30266744, 2018). "The Bax gene is a tumor suppressor gene, and Bcl-2 is an antiapoptotic gene that antagonizes the function of Bax." (PMID 29636773, 2018). "The overexpression of MYC and/or BCL2, doesn’t define a new tumor biology but rather, should be considered as an auxiliary prognostic signature that characterized a subset in DLBCL38." (PMID 29674626, 2018). "For its key role in regulating radiosensitivity of tumor cells, BCL2 was selected as a potential target of miR-153-3p." (PMID 30537994, 2018). "miR-134 can inhibit STAT5B, Hsp90 and Bcl2 and can further inhibit the proliferation, invasion and metastasis of tumor cells." (PMID 29552328, 2018). "Generally, in most of the tumor cells, the mitochondrial membrane potential is controlled by anti-apoptotic genes (e.g., bcl-2, bcl-xl) and pro-apoptotic genes (i.e., bax)." (PMID 29518056, 2018). "While pro-survival BCL-2 expression on its own is mildly oncogenic, acquisition of additional genetic hits is clearly required for tumour formation." (PMID 29769323, 2018). "The ratios of Bax and Bcl-2 protein were determined via western blot to analyze the effect of siRNAs on tumor cell apoptosis." (PMID 30564277, 2018). "Western blots on the tumor samples confirmed that the combination treatment markedly decreased Mcl‐1, c‐Myc, Bcl‐2, and Bcl‐xL." (PMID 29761903, 2018). "These RIG-I-mediated immune responses synergized with siRNA-mediated Bcl2 silencing to promote massive tumor apoptosis in lung metastases in vivo." (PMID 29686682, 2018). "PRP induced tumor cell apoptosis by inhibiting the Jak1–Stat3 pathway and by activating Caspase-3 and Caspase-8 to increase the Bax/Bcl-2 ratio." (PMID 29735884, 2018). "Tamura has found that isoflavones, as plant estrogen, significantly decreased the Bcl-2/Bax ratio, thereby inducing the necrosis and apoptosis of tumor cells." (PMID 30402472, 2018). "The Δ% values of ADC and D were negatively correlated with the Δ% values of tumor size, Ki-67, CA125 and Bcl-2 and were positively correlated with the Δ% values of apoptosis and tumor necrosis." (PMID 30518386, 2018). "This compound binds Bcl-2 protein in vitro with subnanomolar affinities and inhibits tumour growth of chronic lymphocytic leukaemia (CLL) when combined with rituximab in phase II of clinical trial." (PMID 30134553, 2018). "Any increase in the level of Bax or decrease in the level of Bcl-2 can promote tumor cell apoptosis, so Bax/Bcl-2 clearly have a close relationship to the genesis and development of tumors." (PMID 30564277, 2018). "Tumor cells often increase the expression of anti-apoptotic Bcl-2 members to avoid cancer cells undergoing apoptosis." (PMID 29686263, 2018).
tumor (continued). "Reduced expression of miR-15/16 in tumors and their potential to target antiapoptotic target Bcl2 suggested the role of miRNAs as potential tumor suppressors." (PMID 29854719, 2018). "The results showed that the plasma induces apoptosis in the tumor cells by activating the p-53 and Bax/Bcl-2 proteins." (PMID 29769707, 2018). "In contrast, tumor cells overexpressing either Bcl-XL or Bcl-2 were protected against macrophage-mediated killing." (PMID 30083157, 2018). "Xenograft studies confirmed that the expression of BAP1 reduces tumor growth and progression in vivo by lowering the levels of pro-survival factors such as Bcl-2, which in turn diminish the survival potential of the tumor cells." (PMID 29686263, 2018). "Taken together, yeast treatment resulted in a decrease in the expression of both FasL and Bcl2, and an increase in the Bax level relative to animals with tumor alone." (PMID 31098389, 2018). "And the results showed that the tumor treated with dioscin had a significant decrease in the expression of Bcl2, Ki67, and PCNA." (PMID 29497056, 2018). "After 39 days of treatment, it was found that the volumes of tumor for both Bcl-2-siRNA transfected group and the control group were 629 ± 78.9 mm3 and 1914 ± 125.0 mm3 respectively." (PMID 29861465, 2018). "Quercetin and green tea reduced tumor growth in HL-60 xenografts accompanied by decreased expression of anti-apoptotic proteins, BCL-2, BCL-XL and MCL-1 and increased expression of BAX, a pro-apoptotic protein." (PMID 29472583, 2018). "In particular, the miR‐15/16 microRNA family that targets numerous cancer‐relevant factors including the anti‐apoptotic protein Bcl‐2 has been shown to function as a tumor suppressor in various tumors, and we have shown that this is also the case in MPM." (PMID 29094504, 2018). "Cleavage of Par-4 by caspase-3 activates tumor suppression via formation of an approximately 25 kDa fragment (cl-Par-4) that enters the nucleus and inhibits Bcl-2 and NF-ƙB, which function in pro-survival pathways." (PMID 30518159, 2018). "Together, these results confirmed that tumor hyperacetylation caused apoptosis through a RAGE-mediated signaling pathway initiated by binding of Ac-APE1/Ref-1 and alteration of Bcl-2 expression, leading to caspase activation and PARP-1 cleavage." (PMID 29880821, 2018). "A compound can induce apoptosis in tumor cells through several mechanisms, such as blocking the cell cycle, inhibiting the phosphorylation of Bcl-2 and Bcl-xl, activating caspases, up-regulating E2F1, and causing the release of cytochrome c." (PMID 30002625, 2018). "Meanwhile, the transplanted S180 tumor cells exhibited obvious apoptotic phenotype after PPs treatment by arresting the cell cycle in S phase, down-regulating the Bcl-2 expressions and up-regulating the Bax levels." (PMID 30966454, 2018). "Further analyses unveiled that lnc_ASNR exerted a pro-survival role in tumor cells by promoting nuclear retention of the RNA binding protein AUF1 that in physiological conditions mediates BCL-2 mRNA degradation." (PMID 29570632, 2018). "For instance, upregulation of anti-apoptotic Bcl-2 and downregulation of pro-apoptotic Bax in tumor cells are related to the increased resistance to chemotherapy." (PMID 30039180, 2018). "PPs were also shown to induce the transplanted S180 tumor cells apoptosis by arresting the cell cycle in S phase, down-regulating the Bcl-2 expressions and up-regulating Bax levels." (PMID 30966454, 2018). "Primary AML cells have high IRAK1 mRNA levels; IRAK 1 and/or 4 inhibition is antiproliferative; IRAK1/4 inhibitor reduces tumor burden and prolongs survival when combined with Bcl-2 inhibitor or vinblastine." (PMID 30279971, 2018). "Constitutive expression of bcl-2 was observed in numerous primary tumors, which play an important role in tumor cell survival, growth and apoptotic resistance." (PMID 29391428, 2018).